SERPINA12 (serpin family A member 12)
Description:
Adipokine that modulates insulin action by specifically inhibiting its target protease KLK7 in white adipose tissues.
Synonyms: Vaspin; OL-64
Tractability: Antibody: UniProt places it where antibodies can reach, with high confidence; UniProt predicts a signal peptide or a membrane-spanning region; its Gene Ontology location is reachable by antibodies, with medium confidence.
Gene: Protein-coding gene on chromosome 14 (94,487,274 to 94,517,844, reverse strand). Ensembl gene ENSG00000165953.
Subcellular location: Secreted
Gene Ontology:
Molecular function: molecular function inhibitor activity; protein binding; serine-type endopeptidase inhibitor activity
Cellular component: extracellular region; plasma membrane
Genetic constraint (gnomAD): Loss-of-function variants: 21 observed, 27.15 expected, observed/expected ratio (o/e) 0.77, 90% interval 0.55 to 1.11. The upper end of that interval is the gene's LOEUF score, 1.11, which puts it in group 4 of 6, group 1 being the genes least tolerant of losing a copy. Missense variants: 562 observed, 536.03 expected, observed/expected ratio (o/e) 1.05, 90% interval 0.98 to 1.12. Synonymous variants: 220 observed, 207.09 expected, observed/expected ratio (o/e) 1.06, 90% interval 0.95 to 1.19.
Homologues: Orthologues: chimpanzee SERPINA12 (99% identical), macaque SERPINA12 (91% identical), rabbit SERPINA12 (67% identical), dog SERPINA12 (66% identical), rat Serpina12 (63% identical), mouse Serpina12 (61% identical), pig SERPINA12 (61% identical), guinea pig SERPINA12 (51% identical). Paralogues in human: SERPINA1 (38% identical), SERPINA7 (35% identical), SERPINA5 (34% identical), SERPINA3 (34% identical), SERPINA11 (33% identical), SERPINA9 (32% identical), SERPINA4 (31% identical), SERPINA6 (30% identical), SERPINA10 (28% identical), SERPINC1 (28% identical), SERPINB4 (28% identical), SERPINB3 (28% identical), and 24 more.
Diseases named in the same sentence as SERPINA12 in open-access papers:
SERPINA12 is named in the same sentence as 34 diseases in open-access papers, as found by Europe PMC text mining. Sharing a sentence is not in itself a finding about the gene and the disease. The quoted sentences say what the papers report.
Obesity (17 papers, 2012 to 2025). Accumulation of substantial excess body fat. "It is encoded by the SERPINA12 gene, located on the long arm of chromosome 14, and is associated with the development of insulin resistance, obesity and inflammation." (PMID 40491594, 2025). "SerpinA12 is an adipokine that has been linked to the development of insulin resistance, obesity, and inflammation." (PMID 38760690, 2024). "In the study of obesity and insulin sensitivity, mutations in SERPINA12 and MRAP2 have caught our attention." (PMID 38676834, 2024). "The expression of SERPINA12 was positively correlated with obesity and insulin sensitivity, while mutations in MRAP2 were significantly associated with increased obesity risk." (PMID 38676834, 2024). "SerpinA12 was down-regulated in our COVID-19 patients and is associated with diabetes and obesity due to its insulin-sensitizing effects." (PMID 38760690, 2024). "Serpina12 is an adipokine, that is associated with development of insulin resistance, obesity, and inflammation." (PMID 36936413, 2023). "A newly discovered adipokine, visceral adipose tissue-derived serine protease inhibitor (vaspin, SERPINA12) was found to be associated with obesity in human subjects." (PMID 33049941, 2020). "SERPINA12 has been associated with cardiovascular diseases, being implicated in obesity and type 2 diabetes." (PMID 26917578, 2016). "Expression of the serpin vaspin (SERPINA12) is also increased in obesity and type 2 diabetes, but exhibits compensatory roles in inflammation and insulin resistance." (PMID 37152954, 2023). "Vaspin (visceral adipose tissue-derived serpin, serpinA12) is a member of the serine protease inhibitor family of serpins, whose expression shows the highest values when plasma insulin levels and obesity peak, while they are lower in the presence of diabetes." (PMID 30754657, 2019). "One group of genes (SERPINA12, CPE, SERPINA11, MTCH2, PNPLA5, INTS1, APOM) was associated (cosine value >0.1) with obesity and diabetes." (PMID 23544116, 2013). "It is reported that SERPINA12 plays an important role in the progression of obesity and insulin resistance." (PMID 23991084, 2013). "The visceral adipose tissue derived serine protease inhibitor (vaspin, serpinA12) is an adipokine potentially linking obesity, type 2 diabetes (T2D) and insulin resistance (IR)." (PMID 23342091, 2013). "SERPINA12 is identified from visceral adipose tissues of rats, an animal model for obesity and type 2 diabetes." (PMID 23991084, 2013). "Another member of the Serpin family, SerpinA12, is also known as visceral adipose tissue-derived serine protease inhibitor (vaspin), and serves as an adipokine that participates in the development of insulin resistance, obesity, and inflammation by inhibiting kallikreins 7 and 1441." (PMID 39532838, 2024). "Vaspin (also known as SERPINA12) belongs to the serine protease inhibitor family and was identified as an adipokine secreted from visceral AT in the Otsuka Long-Evans Tokushima fatty (OLETF) rat model of obesity and T2DM." (PMID 35909571, 2022). "Visceral adipose tissue derived serine protease inhibitor (vaspin), also known as SERPINA12, is a member of the serpin family, that was first identified in visceral (omental) AT of the Otsuka Long-Evans Tokushima fatty (OLETF) rat, an animal model of obesity and T2D." (PMID 37152954, 2023).
Insulin resistance (7 papers, 2013 to 2025). Increased resistance towards insulin, that is, diminished effectiveness of insulin in reducing blood glucose levels. "Vaspin (SERPINA12) is another adipokine protecting from inflammation and insulin resistance." (PMID 36289764, 2022).
COVID-19 (3 papers, 2021 to 2024). A disease caused by infection with severe acute respiratory syndrome coronavirus 2. "For example, in intensive care unit (ICU) COVID-19 patients there is evidence of a reduction in serpin family A member 12 (SERPINA12) and dipeptidyl peptidase 4 (DPPD-4), which are down regulated by IL-6." (PMID 34361021, 2021). "In COVID-19, the downregulation of SerpinA12 may heighten inflammation via the kallikrein–kinin system." (PMID 38760690, 2024). "Serpin Family A Member 12 (SERPINA12) that is involved in the inhibition of kallikrein-dependent inflammation and is downregulated in critical cases of COVID-19 promoting uncontrolled inflammation and worsening of disease outcome." (PMID 36143338, 2022).
Palmoplantar keratoderma (3 papers, 2021 to 2026). Abnormal thickening of the skin of the palms of the hands and the soles of the feet. "This review summarizes current knowledge on the expression patterns, biological functions, and molecular mechanisms of SERPINA12 in the skin, with a particular focus on adipocytes, psoriasis, and palmoplantar keratoderma." (PMID 42125668, 2026). "Knock-down of SERPINA12 in skin models induced acanthosis and hyperkeratosis, making it a valuable model for functional studies of palmoplantar keratoderma in an in vitro model." (PMID 33652877, 2021). "Furthermore, emerging studies suggest a possible involvement of SERPINA12 in palmoplantar keratoderma, where it may contribute to aberrant keratinization and epidermal barrier dysfunction." (PMID 42125668, 2026).
fatty liver (2 papers, 2021 to 2024). "In the present study, we have identified a novel target, Serpina12, that is suppressed by Sirt6 in the liver and contributing to the onset of liver steatosis when Sirt6 is deficient." (PMID 38332150, 2024). "Sirt6 suppresses Serpina12 in the liver and its deficiency contributes to the onset of liver steatosis and spontaneous tumor development." (PMID 38332150, 2024). "Importantly, CRISPR-Cas9 mediated Serpina12 knockout in the liver ameliorated fatty liver disease caused by Sirt6 ablation." (PMID 38332150, 2024).
hepatocellular carcinoma (2 papers, 2023 to 2025). A malignant tumor that arises from hepatocytes. "Recently, a research find the overexpression of SERPINA12 in hepatocellular carcinoma (HCC) is associated with aggressive clinical features and stemness characteristics." (PMID 37576900, 2023).
metastatic disease (2 papers, 2024). "In particular, PSMB4, RUVBL2 and ANKAR EV protein levels were increased, whereas RAP2B, SERPINA12 and IGLV4-69 abundance levels were decreased in the cEVs of patients with metastatic disease." (PMID 36993200, 2024). "In particular, PSMB4, RUVBL2, and ANKAR EV protein levels were increased in patients with metastatic disease, whereas RAP2B, SERPINA12, and IGLV4-69 abundance levels were decreased in the cEVs of patients with metastasis." (PMID 39693144, 2024).
pancreatic cancer (2 papers, 2024). "We further noticed that some proteins such as PDCD6IP, SERPINA12, KRT20 showed statistically significant population-wise enrichment in pancreatic cancer compared to benign pancreatic diseases." (PMID 36993200, 2024).
psoriasis (2 papers, 2024 to 2026). An autoimmune condition characterized by red, well-delineated plaques with silvery scales that are usually on the extensor surfaces and scalp. "In psoriasis, altered SERPINA12 expression is associated with chronic inflammation, immune dysregulation, and abnormal keratinocyte proliferation, suggesting a potential modulatory role in psoriatic pathogenesis." (PMID 42125668, 2026). "Reduced expression of SerpinA12 in psoriatic keratinocytes leads to increased expression of the interferon-inducible and psoriasis related inflammatory genes (chemokine ligand 20, IL-6, IL-8, and S100 proteins)." (PMID 39737188, 2024). "Some serpins, including SerpinA12, SerpinB2/3//7 play multiple roles in skin barrier function and pathogenesis of psoriasis." (PMID 39737188, 2024). "For example, in an animal model of psoriasis, the application of recombinant vaspin (SerpinA12) reduced infiltration by myeloid cells into the skin." (PMID 39737188, 2024). "Some Serpins, including SerpinA12, SerpinB2/B3/B7, play multiple roles in skin barrier function and pathogenesis of psoriasis." (PMID 39737188, 2024). "SerpinA12 expression is significantly reduced in the lesional skin of psoriasis patients." (PMID 39737188, 2024). "As the main target protease of SerpinA12, KLK7 controls the process of the activation of pro-inflammatory IL-1β and prochemerin, all of which are involved in the pathogenesis of psoriasis." (PMID 39737188, 2024).
Arterial thrombosis (1 paper, 2024). The formation of a blood clot inside an artery. "In VITT02 patient, in whom both venous and arterial thrombosis occurred, a VUS with all damaging predictors of pathogenicity [c.608T>C (p.Leu203Pro)] was found in the SERPINA12 gene." (PMID 39035772, 2024).
breast carcinoma (1 paper, 2024). "The results showed that 5 genes, APOA5, CCDC28B, CCL5, SERPINA12, and WT1, were significantly overexpressed in breast cancer patients (P < 0.05)." (PMID 38676834, 2024).
liver cancer (1 paper, 2024). An epithelial or non-epithelial malignant neoplasm that arises from the liver. "In summary, this study provides a potential mechanism for the ablation of Sirt6, which triggers an increase in Serpina12 upregulation to induce a “lipid-rich” environment that favors liver cancer development." (PMID 38332150, 2024).
lupus (1 paper, 2021). "Additionally, we identified a link between Sufu, Serpina12, and overall hedgehog signaling and the mechanisms governing the expansion of mandibular bone loss in the FcγRIIB-/- model of lupus." (PMID 34548536, 2021). "In this report, we identified Sufu and Serpina12 as candidate regulators of the hedgehog signaling pathway during lupus development." (PMID 34548536, 2021).
nonalcoholic steatohepatitis (1 paper, 2024). "We observed that SERPINA12 expression was significantly increased in nonalcoholic steatohepatitis (NASH) patients compared with an in vitro human liver model (a condition of low glucose and low insulin to mimic the healthy liver)." (PMID 38332150, 2024).
psoriatic arthritis (1 paper, 2024). Joint inflammation associated with psoriasis. "SerpinA12 and SerpinG1 is significantly elevated in the serum of patients with psoriatic arthritis, but its specific mechanism of action in psoriatic arthritis has not been reported." (PMID 39737188, 2024). "SerpinA12 and SerpinG1 are significantly elevated in the serum of patients with psoriatic arthritis, but their specific mechanism of action in psoriatic arthritis has not been reported." (PMID 39737188, 2024).
steatosis (1 paper, 2022). Increased lipid within the cytoplasm of cells. "Serpin family A member 12 (Serpina12, also called vaspin) is protective against alcohol-induced steatosis but is decreased in serum and liver tissues in alcoholic patients and animals." (PMID 35565941, 2022).
cancer (5 papers, 2024 to 2026). A tumor composed of atypical neoplastic, often pleomorphic cells that invade other tissues. "As highlighted in the introduction, the progression of numerous malignant tumors is associated with the abnormal expression of SERPINA12." (PMID 39235554, 2025). "Through pan-cancer analysis, we have identified further malignancies that are linked to SERPINA12, thus supporting the existing literature findings." (PMID 39235554, 2025). "The positive expression rate of SERPINA12 was 49.3% in cancer tissues and 14.7% in adjacent tissues." (PMID 39235554, 2025). "The ductal epithelium of the non‐neoplastic tissue, as well as the low and high‐grade PanIN tissue, showed intermediate staining for SERPINA12, which was homogeneously localized in the cancer cells." (PMID 41211185, 2025). "The results indicated that SERPINA12 expression was positively correlated with individual cancer stages (p < 0.01) and tumor grade (p < 0.01)." (PMID 39235554, 2025). "We examined the expression of SERPINA12 using RNA-seq data in 33 cancer types from the TCGA." (PMID 39235554, 2025). "We conducted a comprehensive review of the existing literature on SERPINA12 in relation to cancer." (PMID 39235554, 2025). "This could be one of the factors contributing to the cancer promoting mechanism of SERPINA12." (PMID 39235554, 2025). "Moreover, ADRB1, CCDC28B, MRAP2, SERPINA12, and WT1 were able to effectively distinguish between normal breast tissue and cancer tissue (AUC > 0.6)." (PMID 38676834, 2024).
tumor (4 papers, 2024 to 2025). "The multivariate Cox regression analysis showed that pathologic T stage, tumor status, and SERPINA12 expression were independently associated with patient survival." (PMID 39235554, 2025). "Our RT-qPCR and immunohistochemical analysis revealed high expression of SERPINA12 in tumor tissues." (PMID 39235554, 2025). "The expression of SERPINA12 in the central (p < 0.001) as well as peripheral tumor compartments (p < 0.001) showed a significant increase in expression compared to non‐neoplastic tissue." (PMID 41211185, 2025). "Understanding the molecular mechanisms of SERPINA12 dysregulation in HCC is crucial for elucidating its role in tumor development." (PMID 39235554, 2025). "From these observations, we hypothesize that SERPINA12 might play a role in regulating the pathways or functions of these immune cells in the tumor microenvironment." (PMID 39235554, 2025). "This suggests that further investigation into the role of SERPINA12 in tumor immune evasion and immune suppression could provide valuable insights." (PMID 39235554, 2025). "ADAMTS13 (p = 0.002), SERPINA12 (p = 0.0186), and MMP12 (p = 0.0049) showed significantly increased expression at the mRNA level in the majority of tumor tissues compared to non‐neoplastic tissue." (PMID 41211185, 2025). "Differential expression analysis of TCGA-LIHC tumor tissues and adjacent normal tissues revealed that the expression differences of TMEM45A, S100A10, SERPINA12, BHMT, CFHR3, RPL8, and STMN1 all exceed a 2-fold change." (PMID 39176099, 2024). "The univariate Cox regression analysis revealed that pathologic T stage, tumor status, and SERPINA12 expression are negative prognostic factors, indicating a worse overall survival (OS) for patients." (PMID 39235554, 2025). "However, despite the similar induction of SERPINA12 and MMP12 expression in the tumor, this does not correlate with survival." (PMID 41211185, 2025).
skin disorder (1 paper, 2026). Any deviation from the normal structure or function of the skin or subcutaneous tissue that is manifested by a characteristic set of symptoms and signs. "Dysregulation of SERPINA12 has been implicated in several skin disorders." (PMID 42125668, 2026). "Understanding the role of SERPINA12 in cutaneous biology may provide new insights into disease pathogenesis and identify potential therapeutic targets for skin disorders." (PMID 42125668, 2026).
SERPINA12 also shares sentences with these, for which no sentence is quoted: diabetes (3 papers); type 2 diabetes (3); brain tumour (1); cardiovascular diseases (1); coronary artery disease (1); diabetic kidney disease (1); Ehlers-Danlos syndrome (1); gastric cancer (1); heart failure (1); Hepatic steatosis (1); inflammation (1); metabolic syndrome (1); morbid obesity (1); Osteopenia (1); periodontitis (1).